NID1 (nidogen 1)
Diseases named in the same sentence as NID1 in open-access papers (continued):
Sharing a sentence is not in itself a finding about the gene and the disease.
tubulointerstitial nephritis (1 paper, 2020). "Notably, the mix of ADAMTS5-affected matrix proteins was enriched in basement-membrane components including laminins (LAMA/LAMB/LAMC), collagen-6 (COL6A1/A2), collagen-12 (COL12A1), AGRN, nidogen-1 (NID1), and TINAG (tubulointerstitial nephritis Ag)." (PMID 32917786, 2020).
tumor (48 papers, 2011 to 2025). "Interruption of Nidogen-1 expression reduces the tumor cell susceptibility to neutrophil cytotoxicity, which accords with our previous data demonstrating that knockout of RAGE expression confers resistance to neutrophil cytotoxicity." (PMID 35453656, 2022). "Moreover, Nidogen-1 was found to bind tumor cell-associated Hspg2, suggesting that these components form complexes on the cell surface." (PMID 35453656, 2022). "While shRNA to Hspg2 barely affected neutrophil cytotoxicity, shRNA to Nidogen-1 reduced tumor cell susceptibility to neutrophil cytotoxicity, suggesting that Nidogen-1 contributes to the neutrophil recognition of tumor cells required for the subsequent cytotoxic effect." (PMID 35453656, 2022). "We have also performed CD31 and nidogen-1 co-localization immunofluorescent staining in 4T1 primary tumor samples, and the co-localization results supports nidogen-1 is located at the BM surrounding vessels." (PMID 41181108, 2025). "To investigate which cells were producing nidogen-1, we used RNAScope technology to visualize nidogen-1 mRNAs in the border region of the 4T1 tumor and the healthy fat pad." (PMID 41181108, 2025). "NID1 has been described to promote tumor cell migration, invasion, epithelial-to-mesenchymal transition (EMT) and chemo-resistance in different tumors similarly to MCAM." (PMID 40342827, 2025). "In CRC, loss of N‐Myc downstream‐regulated gene 4 (Ndrg4) function in organoid models triggered neuronal secretion of tumor-promoting factors, including nidogen 1 and fibulin 2, identifying novel therapeutic targets within neurogenic signaling pathways." (PMID 41163091, 2025). "The identified integrin interactors, FN, collagen alpha-2(IV) chain (constituent of collagen type I), serpin H1, NID-1, and 4-PH alpha-1 protein, were found to be more abundant in the deep tumor samples." (PMID 39195201, 2024). "FN, collagen alpha-2(IV) chain, serpin H1, and NID-1 were found to be, instead, more-abundant proteins in D tumor samples, while 4-PH alpha-1 was more abundant in S samples and not detected in healthy control samples." (PMID 39195201, 2024). "Nidogen‐1 (NID1), a basement membrane component reported to be upregulated in tumor occurrence, can enhance the invasion and metastasis of tumor." (PMID 39092293, 2024). "This shows that extracellular NID1 acts as a tumor suppressor gene, while intracellular NID1 acts as a tumor-promoting gene." (PMID 38250812, 2023). "When the tumor invades through the basement membrane, NID1 is shed into extracellular fluids, and the soluble NID1 can bind to NKp44 to further impair the NK cell functions to promote immune evasion." (PMID 36750830, 2023). "We also examined the expression of LAMB1 and NID1 in human pNF tumor samples and found that both were abundantly deposited in human pNF samples compared with normal sciatic nerve." (PMID 37140985, 2023). "We further observed that the CLRs interact with tumor Nidogen-1 and Hspg2, two sulfated glycoproteins of the basement membrane." (PMID 35453656, 2022). "Since Hspg2 is also expressed on the surface of the tumor cells, and Nidogen-1 interacts with Hspg2, it is likely that Nidogen-1 binds to tumor cell surface through Hspg2." (PMID 35453656, 2022). "Using mouse models of cancer, we have presented data showing that the two CRLs Dectin-1 and Clec4e on neutrophils are co-operating in recognizing Nidogen-1 and Hspg2 on the tumor cell surface." (PMID 35453656, 2022). "In HCC, FAM-CSG colocalized with its target receptor, the laminin and nidogen-1 complex, which is expressed in tumor ECM." (PMID 35273916, 2022). "Nidogen-1 (NID1) was downregulated in all tumor types, while NID2 was downregulated only in SCLC, compared to adjacent tissue." (PMID 35681609, 2022). "To study the involvement of tumor expressed Nidogen-1 in neutrophil cytotoxicity, we used specific shRNA to knock down the expression of Nidogen-1 and Hspg2 in AT3 and LLC cells." (PMID 35453656, 2022).
tumor (continued). "Although Nidogen-1 is an essential component of the basement membrane, we observed that Nidogen-1 is also expressed on the tumor cell surface, and that the Nidogen-Fc fusion protein can bind to the tumor cells." (PMID 35453656, 2022). "RAGE is one of the receptors on the tumor cells that assist keeping Nidogen-1 and Hspg2 on the tumor cell membrane." (PMID 35453656, 2022). "Taken together, Nidogen-1 on the tumor cell surface contributes to the interaction between neutrophils and tumor cells required for the subsequent tumor cell death." (PMID 35453656, 2022). "We further show that Nidogen-1 binds to the surface of tumor cells through the G2-domain which is known to be the binding domain of Nidogen-1 to Hspg2." (PMID 35453656, 2022). "Altogether, this study suggests a role for CLR–Nidogen-1 interaction in the recognition of tumor cells by neutrophils, and this interaction facilitates neutrophil-mediated killing of the tumor cells." (PMID 35453656, 2022). "In this study, we report the use of superparamagnetic iron-oxide nanoparticles (IO-NP) conjugated to a nonapeptide, CSGRRSSKC (CSG), which specifically binds to the laminin-nidogen-1 complex in tumours." (PMID 34683956, 2021). "The laminin-nidogen-1 complex is highly conserved in mouse and human tumours and clearly represents a robust molecular target." (PMID 34683956, 2021). "RIP1-Tag5 tumours express two- to three-fold higher laminin-nidogen-1 complex than the normal exocrine pancreas." (PMID 34683956, 2021). "Our study showed that the NID1 level in circulating EVs from mice increased progressively with the bioluminescence signal, which reflects the tumor burden in the animals." (PMID 33173740, 2020). "Meanwhile, miR-1298-3p agonist markedly decreased the protein levels of NID1 and vimentin, but increased the protein level of E-cadherin in tumor tissues, compared with NC group." (PMID 32355035, 2020). "We also identified tumor specific increases of nidogen 1, decorin, perlecan, and of six laminin subunits." (PMID 21731504, 2011). "However, nidogen-1 staining was stronger in the healthy fat pad region as compared to the tumor region." (PMID 41181108, 2025). "Both nidogen-1 and collagen IV were present at the tumor region and the healthy fat pad region." (PMID 41181108, 2025). "In addition, we provided deeper characterization of nidogen-1 from higher magnification immunofluorescent staining images showing detailed views of nidogen-1 in primary 4T1 tumor in fat pad area and in lung metastasis of 4T1 tumor area." (PMID 41181108, 2025). "In addition, in that study, we also observed discontinuous nidogen-1 coverage of the BMs at the invasive tumor front." (PMID 41181108, 2025). "Here, we performed a comprehensive bioinformatics analysis of multiple datasets derived from CRC patients and showed that elevated expression of NID1 and the genes ITGA3, ITGB1, and ITGAV, which encode NID1 receptors, is associated with poor prognosis and advanced tumor stage." (PMID 38001576, 2023). "Both Nidogen-1 and Hspg2 were found to be expressed on the tumor cell surface." (PMID 35453656, 2022). "Taken together, our study suggests that CLR recognition of tumor Nidogen-1 may facilitate the neutrophil-tumor cell interaction required for the subsequent cytotoxic step." (PMID 35453656, 2022). "The knockdown of Nidogen-1, but not that of Hspg2, led to reduced susceptibility of the tumor cells to neutrophil cytotoxicity." (PMID 35453656, 2022). "For example, several components of the basement membrane (e.g., Collagens, Nidogen-1, Laminin subunit 3) were downregulated in tumor tissue, and proteins involved in Calcium-ion binding (e.g., Annexin-A3, S100A4) showed lower expression levels in tumor tissue than in tumor-adjacent tissue." (PMID 35681609, 2022). "This makes Nidogen-1 a tumor component that can be recognized by neutrophils." (PMID 35453656, 2022).
tumor (continued). "Importantly, unlike normal tissue ECM that is expressed exclusively as a thin basement membrane supporting vessels and epithelia, in tumours, laminin and nidogen-1 are also aberrantly expressed as avascular ECM." (PMID 34683956, 2021). "Knockdown of NID1 resulted in diminished ability of the tumor cells to grow, migrate, and invade." (PMID 33173740, 2020). "In addition, we analyzed the mRNA expression of NID1 in GEO GSE79973 dataset and found that NID1 expression was significantly higher in GC compared with non-tumor gastric tissues." (PMID 32157097, 2020). "However, in the future, a deeper understanding of the molecular mechanisms regulating tumor growth by miR-1298-3p/NID1 axis require further investigation." (PMID 32355035, 2020). "Published evidence and our data suggest that nidogen-1 might play a dual role in cancer cell migration depending on the tumour type and the microenvironmental context." (PMID 30947697, 2019). "In addition, NID1 can also be exposed at the cell surface of different NID1-releasing tumor cell lines." (PMID 31024551, 2019). "Consequently, the release of soluble NID1 was proposed to be a novel immunosuppressive mechanism exploited by tumor cells to evade NK cell surveillance." (PMID 31134055, 2019). "Interestingly, sRAGE-Fc bound Nidogen-1-Flag to a certain extent, suggesting that there may be a functional/physical link between tumor cell Nidogen-1 and RAGE and the C-type lectin receptors on neutrophils." (PMID 35453656, 2022). "Knockdown of Nidogen-1, but not of Hspg2, in tumor cells reduced their susceptibility to neutrophil cytotoxicity, suggesting that Clec4e/Dectin-1 contribute to the recognition of tumor cells through interaction with Nidogen-1." (PMID 35453656, 2022). "shRNA to Nidogen-1, but not shRNA to Hspg2, caused significant reduction in the sensitivity of tumor cells to neutrophil-mediated cytotoxicity, suggesting a role for Nidogen-1 in neutrophil recognition of tumor cells." (PMID 35453656, 2022). "Interestingly, the Nidogen-1/Hspg2 complex was also found to interact with tumor RAGE." (PMID 35453656, 2022). "The deep region of the tumor was accurately classified by sorting nexin-18 and beta-COP, while peptide YY (PYY), NID-1, and XRCC1 contributed weakly." (PMID 39195201, 2024). "We have previously reported a tumor extracellular matrix (ECM)-targeting peptide, CSG, that specifically binds to the aberrant network of laminin-nidogen-1 complex in a number of mouse and human solid tumors including breast, pancreatic and liver cancers." (PMID 35273916, 2022). "miR-767-3p reduces NID1 expression and inactivates the NID1/PI3K/Akt/EMT pathway to reduce tumor growth in NSCLC." (PMID 34503180, 2021). "CREKA-IO-NP binding in tumours correlates with the location of CD31-positive endothelia, whereas CSG-IO-NP binding correlates mainly with tumour ECM detected with collagen I, laminin and nidogen-1 staining." (PMID 34683956, 2021). "EVs‐NID1 also activates fibroblasts that secrete TNF receptor 1 (TNFR1), promote lung colonization of tumor cells, and augment the growth and motility of cancer cells." (PMID 34977870, 2021). "Previously, we showed that the target for CSG binding, the laminin-nidogen-1 complex, is an extensive network formed throughout the RIP1-Tag5 tumours and overlaps with fibrillar collagens including collagen-1." (PMID 34683956, 2021). "Actually, the functional outcome of the NKp44-NID1 interaction may be rather complex, as NID1 can associate with other ECM components, including laminin, collagen type IV, and perlecan, or be modified by extracellular proteases secreted in the tumor microenvironment." (PMID 31024551, 2019). "In other tumour types, ETV5 has been found to mediate EMT through modulation of invasion-related genes, such as NID1, MMP2 and FOXM130,53,54." (PMID 30952872, 2019). "In the orthotopic model, we did not observe any difference in primary tumor growth rate between wildtype and nidogen-1 knockout mice." (PMID 41181108, 2025).
tumor (continued). "Beta-COP, NID-1, and XRCC1 could be considered tumor-promoters playing a role mainly in the part of the tumor that invades and progresses into the internal tissues of the colon, and from which CRC cells migrate, mature and metastasize." (PMID 39195201, 2024). "In addition, the CLR receptors Dectin-1 and Clec4e on neutrophils interact with Nidogen-1/Hspg2 expressed on the tumor cell surface, some of which also interact with the tumor RAGE, thus bridging the neutrophils to the tumor cells." (PMID 35453656, 2022). "The finding that both tumor RAGE and CLRs interact with Hspg2/Nidogen-1, suggests that Hspg2/Nidogen-1 might bridge between RAGE and CLRs, and thus strengthen the neutrophil-tumor cell synapse." (PMID 35453656, 2022). "Notably, the Nidogen-1/Hspg2 complexes also interact with tumor RAGE, suggesting that these extracellular matrix molecules strengthen the neutrophil-tumor cell synapse by bridging CLRs with RAGE." (PMID 35453656, 2022). "For the ITGA4, ITGA9, NID1 and NID2 genes for which XmaI-RRBS data are available, we have calculated the relative fractions of methylated and nonmethylated alleles in tumor samples, in respect to HER2 expression in tumors." (PMID 33500458, 2021). "In addition, western blotting revealed that expression levels of NID1, p-Akt and p-ERK were all significantly reduced in tumor tissues expressing hsa_circ_0018818 shRNA1." (PMID 32357143, 2020). "Specifically, NID1, secreted from extracellular vesicles (EVs) in metastatic HCC enhanced the pre-metastatic niche formation in lung through increasing angiogenesis and the pulmonary endothelial permeability, thereby promoting tumor cells colonization and extrahepatic metastasis." (PMID 41281746, 2025). "Furthermore, Western blotting assay indicated that the expression of NID1 was consistent with ETV4 and LOXL2 in paired non-tumor and tumor tissues samples (n=4), and the correlation analysis on human CRC cDNA array showed that NID1 was positively correlated with ETV4 and LOXL2, respectively." (PMID 41281746, 2025). "Interestingly, co-immunoprecipitation studies show that sRAGE-Fc binds endogenous Hspg2 and Nidogen-1, suggesting that tumor RAGE may contribute to their binding to the tumor cell surface." (PMID 35453656, 2022). "Here, it is found that nidogen 1 (NID1) in metastatic HCC cell‐derived extracellular vesicles (EVs) promotes pre‐metastatic niche formation in the lung by enhancing angiogenesis and pulmonary endothelial permeability to facilitate colonization of tumor cells and extrahepatic metastasis." (PMID 33173740, 2020). "However, despite the nearly complete absence of FN in the tumor, basement membrane components ColIV, laminin, Nid-1 and Nid-2 appeared to be properly assembled." (PMID 25807551, 2015).
cancer (31 papers, 2007 to 2026). A tumor composed of atypical neoplastic, often pleomorphic cells that invade other tissues. "Our findings uncover a novel role of stromal nidogen-1 in the regulation of cancer progression and identify lung BM defects upon loss of nidogen-1 that enable formation of metastases." (PMID 41181108, 2025). "We set forth to look at Nidogen-1 and Hspg2, as these are highly sulfated glycoproteins implicated in cancer metastases, and we (this paper) and others observed that these basement membrane components are also expressed on the cell surface." (PMID 35453656, 2022). "This suggests that loss of nidogen-1 may cause BM defects, which compromise its barrier function, thereby increasing the ability of cancer cells to extravasate and colonize the lungs." (PMID 41181108, 2025). "We therefore hypothesized that loss of nidogen-1 may cause BM defects in the lungs, which compromise BM barrier function, thereby increasing the ability of cancer cells to extravasate and colonize the lungs." (PMID 41181108, 2025). "This led us to hypothesize that loss of nidogen-1 in the stromal compartment may promote cancer cell invasion and metastasis." (PMID 41181108, 2025). "Additionally, there are several aME genes whose dysregulation is associated with cancers when misregulated, such as Mmp14, Nid1, Mdm2, Cd36, and Id3." (PMID 41223055, 2025). "In this study, we identify a 4-protein sEV biomarker panel (thrombospondin-1, nidogen-1, pentraxin-3, and versican) based on proteomic profiles obtained from an isogenic cancer cell line model." (PMID 41881025, 2026). "These newly described defects indicate compromised BM barrier function, which can explain the increased metastatic capacity of cancer cells in colonizing the lungs of nidogen-1 knockout mice." (PMID 41181108, 2025). "Taken together, our findings provide novel insight into cancer-stromal interplay and uncover new roles of nidogen-1 in the regulation of cancer metastasis." (PMID 41181108, 2025). "Our findings provide novel insight into cancer-stromal interplay and the role of nidogen-1 at the metastatic niche." (PMID 41181108, 2025). "Our studies therefore uncover novel functions of nidogen-1 in regulating cancer progression and highlight the roles of stromal cell-derived nidogen-1." (PMID 41181108, 2025). "Here, we investigate the role of stromal nidogen-1 in cancer metastasis using nidogen-1 knockout mice." (PMID 41181108, 2025). "It is worthwhile to understand how NID1 is particularly packaged and secreted in the form of EVs by cancer cells." (PMID 33173740, 2020). "What’s more, high expression of NID1 in GC tissues also predicted poor survival outcome of cancer patients and NID1 knockdown prohibited migration and invasion of cancer cells via partially inducing MET." (PMID 32157097, 2020). "The basal membrane with nidogen-1 as one of its components serves as a strong barrier for cancer cells." (PMID 30947697, 2019). "With the identification of nidogen-1 as an inhibitor of cancer cell migration, we characterized an endothelial cell-derived regulator critical for malignant tumour progression." (PMID 30947697, 2019). "The identification of nidogen-1 as an endothelial-derived inhibitor of migration of distinct cancer cell types reveals a novel mechanism of endothelial control over cancer progression." (PMID 30947697, 2019). "Quiescent endothelial cells exert control over cancer cell migration by releasing inhibitory factors such as nidogen-1." (PMID 30947697, 2019). "Down-regulation of the nidogens (NID1 and NID2) de-stabilizes the basement membrane and has been associated with cancer formation." (PMID 25093596, 2014). "High NID1 expression correlates with disease progression in several types of cancers." (PMID 37140985, 2023). "Our results indicated that folic acid inhibited the expression of MTHFD2 and NID1, speculating that folic acid may inhibit the expression of MTHFD2 and NID1, and it may be used in cancer treatment in the future." (PMID 34604366, 2021).